IL7 (interleukin 7)
Diseases named in the same sentence as IL7 in open-access papers (continued):
Sharing a sentence is not in itself a finding about the gene and the disease.
osteoporosis (4 papers, 2021 to 2025). A condition of reduced bone mass, with decreased cortical thickness and a decrease in the number and size of the trabeculae of cancellous bone (but normal chemical composition), resulting in increased fracture incidence. "Specifically, the total MR Effect size between SNPs of IL-2, IL-7, and osteoporosis were presented by forest plots, the IVW method was used as the main analysis method." (PMID 37949959, 2023). "In addition, IL-7/IL-7r can promote the RANKL-mediated osteoclast formation and bone resorption by activating the c-Fos/c-Jun pathway, as well as inducing bone loss in ovariectomized mice, a model of osteoporosis." (PMID 34206780, 2021). "For instance, MR research has concluded a positive link of interleukin-7 (IL-7) levels with osteoporosis, while other interleukins have exhibited no noticeable linkage with the disease." (PMID 41329541, 2025).
respiratory failure (4 papers, 2020 to 2024). The significant impairment of gas exchange within the lungs resulting in hypoxia, hypercarbia, or both, to the extent that organ tissue perfusion is severely compromised. "Respiratory failure was signified by depression of EGF, GZMA, LAP, IL-4, and IL-7, and increased expression of MUC-16, ARG-1, and LAMP-3." (PMID 34177897, 2021).
sarcoma (4 papers, 2020 to 2025). A usually aggressive malignant neoplasm of the soft tissue or bone. "In metastatic pediatric sarcomas including osteosarcoma and Ewing sarcoma, adjuvant therapy with recombinant IL-7 was shown to promote immune recovery and CD4 count recovery compared with standard therapy." (PMID 39086683, 2023). "IL7 treatment promotes immune reconstitution significantly and improves the overall survival of pediatric sarcoma patients." (PMID 32793475, 2020). "Lastly, a recent clinical trial using rh‐IL‐7 as adjuvant therapy every 2 weeks combined with dendritic cell vaccination or autologous lymphocyte infusion led to significantly better OS in pediatric sarcoma patients compared to that of the patients in a historical control cohort." (PMID 36583472, 2023). "Although IL-7 is crucial for lymphocyte maintenance, a sarcoma clinical trial showed that adjuvant IL-7 increased T cell infiltration without providing anti-cancer benefits." (PMID 40707961, 2025).
septic shock (4 papers, 2023 to 2025). Shock caused by infection; frequently caused by gram negative bacteria, although some cases have been caused by other bacteria, viruses, fungi, and protozoa; characterized by fever, chills, tachycardia, tachypnea, and hypotension. "In the IRIS-7 RCT, CYT017, a recombinant form of IL-7, was administered at both low and high doses in patients with septic shock and lymphopenia." (PMID 40007937, 2025).
synovitis (4 papers, 2014 to 2024). Inflammation of a synovial membrane. "In arthritic conditions, IL-7 promotes expansion of lymphocytes associated with Th1 and Th17 activity, augmenting the severity of the disease, including synovitis, pannus, and bone and cartilage erosion." (PMID 29104576, 2017). "IL-4, IL-18, IL-7, and IL-12 represent effector cell function and are involved in the perpetuation of synovitis and chronic synovitis." (PMID 38675400, 2024). "Across the pro-inflammatory biomarkers, there were relationships seen with IL-7 to radiographic OA, IL-8 with effusion-synovitis and TNF with increased quality of life." (PMID 37877037, 2023). "We have previously discussed the discrepancy between low systemic IL-7 and high synovial expression in relation to progression of bone erosion suggesting that reduced systemic IL-7 is an indicator of active synovitis." (PMID 25533722, 2014).
T-cell lymphoma (4 papers, 2021 to 2023). "Cytokines like IL-2 and IL-7 are well-established mediators of T-cell lymphoma metabolic reprogramming." (PMID 37746258, 2023). "Furthermore, gain-of-function alterations in the IL-7 signaling pathway were identified in the majority of T-cell lymphomas (reviewed by Waldmann and colleagues)." (PMID 34066732, 2021). "Interleukin-7 (IL-7) is a cytokine produced by stromal cells and promotes hematological malignancy development and differentiation (ALL, T-cell lymphoma)." (PMID 34026651, 2021). "IL-7 transgenic mice displayed accelerated mortality due to T- and B-cell lymphoma development and also AKR/J mice, which overexpress wild type IL-7Rα, spontaneously developed T-cell lymphoma." (PMID 34066732, 2021).
ZIKV infection (4 papers, 2018 to 2022). "The results suggest that ZIKV infection cells hinder JEG3 cell cycle control, the ERAD pathway, and IL-7 interactions and promote mRNA decay and processing (as well as alternative splicing) and the IL-2 pathway." (PMID 36015056, 2022). "Cytokines and chemokines with higher levels during acute ZIKV infection were IP-10, RANTES, IFN-γ, IL-9, IL-7, IL-1ra, and IL-5, involving innate and adaptive immune responses." (PMID 29774022, 2018). "In this more stringent analysis, the frequency difference of IFN-γ was no longer significant, whereas IL-5 and IL-7 showed higher frequency of detection in acute ZIKV infection in relation to the normal physiological state." (PMID 29774022, 2018).
acute coronary syndrome (3 papers, 2017 to 2021). Signs and symptoms related to acute ischemia of the myocardium secondary to coronary artery disease. "The elevated levels of IL-7 have been shown in patients with acute coronary syndrome." (PMID 33985567, 2021).
anemia (3 papers, 2021 to 2023). A reduction in the number of red blood cells, the amount of hemoglobin, and/or the volume of packed red blood cells. "Despite that, reduced peripheral levels of IL-7 have been associated with inefficient erythropoietic responses in P. falciparum-induced severe anemia." (PMID 33791239, 2021). "Trend analysis of IL-2, IL-5, FGF, PDGF-bb, IL-17, CCL5, IL-4, IL-13, IFN-γ, IL-7 and TGF-β1 uncovered that as the severity of anemia increased, the concentrations of these inflammatory molecules decreased." (PMID 37143662, 2023).
angina pectoris (3 papers, 2019 to 2024). The symptom of paroxysmal pain consequent to MYOCARDIAL ISCHEMIA usually of distinctive character, location and radiation. "In another clinical study, IL-7 plasma levels were found to be increased in patients with stable and unstable angina compared to healthy controls and heightened the expression of chemokines in circulating mononuclear cells; IL-7 levels were reduced with aspirin administration." (PMID 38256155, 2024).
Anorexia (3 papers, 2010 to 2020). Lack of desire to eat (loss of appetite). "Importantly, contrary to other cytokines described to induce anorexia secondary to nausea, we demonstrate that this modulation of feeding is mediated by IL-7 per se and not by sickness." (PMID 20376352, 2010).
atopic dermatitis (3 papers, 2023 to 2025). "A decrease in IL-7 has been related to increased severity of atopic dermatitis in mice through up-regulation of the Th2 immune response." (PMID 40929127, 2025).
benign prostatic hyperplasia (3 papers, 2011 to 2022). A non-cancerous nodular enlargement of the prostate gland. "The significance of IL-7 elevation in advanced adenomas needs further clarification, but it might be of interest to mention that in benign prostatic hyperplasia IL-7 has been shown to stimulate proliferation of the prostatic cells." (PMID 27866242, 2017). "We evaluated local IL-2, IL-7, IL-15 and IL-21 gene expression in prostate tissues from patients with early stage PCA or benign prostatic hyperplasia (BPH)." (PMID 21943235, 2011).
Cachexia (3 papers, 2018 to 2026). Severe weight loss, wasting of muscle, loss of appetite, and general debility related to a chronic disease. "Furthermore, exercise-derived myokines such as IL-7, IL-15, and IL-6 act systemically, promoting T cell and NK cell survival while simultaneously exerting anti-inflammatory effects that may mitigate cancer-related cachexia and support immune competence." (PMID 41562839, 2026). "Specifically, IL-7 levels are significantly elevated in cancer patients with cachexia compared to those without cachexia, and the promotion of differentiation and activation of T cells by IL-7 may lead to muscle wasting and weight loss." (PMID 38675377, 2024).
cardiomyopathy (3 papers, 2018 to 2025). A disease of the heart muscle or myocardium proper. "The gene expression of CXCL9, coding for MIG in monocytes, was also low in patients with cardiomyopathy, suggesting that IL-27/IL-27R and IL-7/IL-7R may be altered in other cell types." (PMID 34061845, 2021). "CD4+ T cell responses improved after in vitro treatment with IL-27 and IL-7 only in subjects without signs of heart disease who have a more functional IL-27 and IL-7 axis and less exhausted immune system compared with those in patients with severe cardiomyopathy." (PMID 34061845, 2021). "This hypothesis was particularly demonstrable in IFN-γ producers with severe cardiomyopathy, who exhibit normal values of IL-7 and sCD127 but decreased responses to IL-7 by the inverse association between IFN-γ producing cells and circulating sCD127." (PMID 30517089, 2018). "Decreased CD25 upregulation in response to IL-7 in CD4+ T cells was observed in IFN-γ nonproducers with severe cardiomyopathy compared with IFN-γ producers and uninfected subjects." (PMID 30517089, 2018). "In contrast, IFN-γ nonproducers with severe cardiomyopathy exhibited an impaired capacity to respond to IL-7." (PMID 30517089, 2018). "In vitro treatment of PBMCs with IL-27 and IL-7 improved monofunctional and polyfunctional Th1 responses, accompanied by the induction of IL-10 and Bcl-2 expression in subjects without heart disease but did not improve those in subjects with cardiomyopathy." (PMID 34061845, 2021).
chronic rhinosinusitis (3 papers, 2021 to 2024). Chronic form of sinusitis. "Therefore, our aim is to investigate the complex appearance, relative distribution and interlinks of IL-1, IL-4, IL-6, IL-7, IL-8, IL-10, IL-12 and Ki 67 in chronic rhinosinusitis with nasal polyps (CRSwNP) affected human nasal mucosa." (PMID 34208325, 2021). "Our aim was to use detected IL-1, IL-4, IL-6, IL-7, IL-8, IL-10, IL-12, Ki 67, HBD-2, HBD-3, and LL-37 to classify specific inflammatory endotypes in chronic rhinosinusitis with the tissue of nasal polyps (CRSwNP)." (PMID 38791197, 2024). "Therefore, our aim was to use detected IL-1, IL-4, IL-6, IL-7, IL-8, IL-10, IL-12, Ki 67, HBD-2, HBD-3, and LL-37 to classify specific inflammatory endotypes in chronic rhinosinusitis with the tissue of nasal polyps (CRSwNP)." (PMID 38791197, 2024). "IL-7 levels are thought to increase in cases of chronic inflammatory diseases such as inflammatory bowel or Chron’s disease, yet it has not been extensively evaluated in chronic rhinosinusitis." (PMID 36285981, 2022).
coronary heart disease (3 papers, 2020 to 2025). "In coronary heart disease, there is a higher expression of TIM3 in CD4+ T lymphocytes in peripheral blood, along with an increase in the expression of the hematopoietic growth factor IL-7 in blood." (PMID 41325840, 2025).
esophageal cancer (3 papers, 2019 to 2025). A primary or metastatic malignant neoplasm involving the esophagus. "However, higher levels of IL-7 were found to be associated with several diseases, such was fibromyalgia and also in patients with colorectal and esophageal cancers compared to healthy controls." (PMID 33731158, 2021). "In addition to previously observed elevation of IL-7 at the systemic level in CRC, also esophageal cancer was associated with the oversecretion of IL-7." (PMID 31185636, 2019). "In a subgroup of patients with esophageal cancer, the mean difference was lower than the entire cohort average, but mean IL-7 concentration in tumors was higher than in normal tissue: 45.1 pg/g (33.9–56.3) vs. 25 pg/g (15.2–34.8)." (PMID 31185636, 2019).
fungal infection (3 papers, 2018 to 2024). "These benefits of IL-7, anti-PD-1, and anti-PD-L1 immuno-adjuvant therapy in patients with viral and fungal infections support their potential efficacy in patients with MDR bacteria." (PMID 29944697, 2018). "The antifungal cytokines—Type1 (IL-7 and IL-15), Th17 (IL-7), and proinflammatory (IL-11)—were all significantly enhanced in CBM patients, presumably as a compensatory response to the long-term fungal infection." (PMID 35252030, 2022).
gastric tumors (3 papers, 2019 to 2022). "Mean IL-7 concentration in gastric tumors was higher than in normal tissue: 61.1 pg/g (37.7–84.6) vs. 20.4 pg/g (4.8–35.9)." (PMID 31185636, 2019). "The expression of PTGS2, BCL2, and IL7 (inversely) was independently associated with CCL2 in non-cancerous tissue, explaining 88% in gene variability, and HIF1A and BCL2 were independently associated with CCL2 in gastric tumors, explaining 83% in its variation." (PMID 32630408, 2020).
head and neck cancer (3 papers, 2014 to 2024). A primary or metastatic malignant neoplasm affecting the head and neck. "Serum IL-7 was identified as a diagnostic marker in head and neck cancer." (PMID 25533722, 2014). "There are several ways that MSCs can promote drug resistance in cancer cells, mostly through the secretion of cytokines like IL-6, IL-7, and IL-8, for example, in head and neck carcinomas, where these molecules induce paclitaxel resistance." (PMID 38674102, 2024).
leukocytosis (3 papers, 2012 to 2022). "IL-7 promotes leukocytosis by inducing proliferation of lymphocytes; it also increases WBC by stimulating secretion of IL-1, IL-6, and tumor necrosis (TNF) factor from circulating lymphocytes, monocytes, and macrophages." (PMID 22844297, 2012).
liver disease (3 papers, 2022 to 2025). "Mitigating the IL-7/IL-7R axis could enhance immune surveillance and provide a therapeutic approach to liver disease management." (PMID 40408005, 2025). "Targeting IL-7/IL-7R could offer a therapeutic approach for fibrosis-related liver diseases." (PMID 40408005, 2025).
liver inflammation (3 papers, 2023). "Circulating IL-7 levels were decreased in patients with chronic hepatitis C (HCV) infection and were negatively correlated with viral replication and liver inflammation." (PMID 35801423, 2023).
lung adenocarcinoma (3 papers, 2022 to 2024). A carcinoma that arises from the lung and is characterized by the presence of malignant glandular epithelial cells. "Therefore, IL-7 can be used as a beneficial prognostic marker with the potential to be applied in the treatment of lung adenocarcinoma patients." (PMID 38675377, 2024). "The genes that increased with fivefold following co‐culture with all lung adenocarcinoma cell lines were CD80 (B7‐1), IL‐7, IL‐15, and TNF." (PMID 34907653, 2022).
metastatic cancer (3 papers, 2018 to 2021). A carcinoma which has spread from the original site of growth to another anatomic site. "In metastatic cancer, FRCs appear to be regulated by the tumor cells decreasing IL-7 secretion and enhancing other soluble factors, causing alterations in the lymph node structure, such as fibrosis." (PMID 34068712, 2021). "The first clinical trial using IL-7 examined the therapeutic effects of IL-7 administered to humans with metastatic cancer." (PMID 29416551, 2018).
metastatic melanoma (3 papers, 2019 to 2022). A melanoma that has spread from its primary site to another anatomic site. "To further explore IL7 expression and genotypic association of rs16906115 across B cell subsets, we generated scRNA-seq data from B cells (n = 15,755 cells) from pre-treatment patients with metastatic melanoma (n = 24) and healthy controls (n = 5)." (PMID 36526722, 2022). "IL-7 is a cytokine from the IL-2 family, with IL-2 treatment in low or high doses in patients with metastatic melanoma identified as successful immunotherapy." (PMID 33574842, 2021). "IL-7 levels were significantly lower in metastatic melanoma patients than those in healthy controls." (PMID 33574842, 2021).
Myalgia (3 papers, 2017 to 2025). "The second study reported that IL-7 was among nine plasma proteins that could distinguish TMD myalgia from healthy, pain-free controls with the highest discriminative power (66% higher than controls)." (PMID 40142185, 2025). "The main findings were that the masseter levels of IL-6, IL-7, IL-8 and IL-13 were higher in TMD myalgia patients than controls and that repetitive tooth-clenching increased the levels of IL-6 and IL-8 in both groups, while IL-7, IL-13 and TNF increased only in patients." (PMID 28243900, 2017). "The first study reported elevated masseter muscle levels of IL-6, IL-7, IL-8, and IL-13 in patients with TMD myalgia compared to a control group." (PMID 40142185, 2025). "Interleukin 6 (IL-6) and interleukin 8 (IL-8) levels increased in response to tooth clenching in both groups, while interleukin 7 (IL-7), interleukin 13 (IL-13) and tumor necrosis factor (TNF) rose only in patients with TMD-related myalgia." (PMID 37509035, 2023). "Microdialysis revealed that the levels of IL-6, IL-7, IL-8 and IL-13 were higher in patients with TMD-related myalgia than controls." (PMID 37509035, 2023). "This study showed that the muscle levels of IL-6, IL-7, IL-8 and IL-13 were increased in patients with TMD myalgia and increased further in response to experimental tooth-clenching, as did jaw-muscle pain and fatigue." (PMID 28243900, 2017). "Tooth-clenching increased IL-6, IL-7, IL-8, TNF and IL-13 in TMD myalgia patients and IL-6 and IL-8 in controls, in line with previous studies." (PMID 28243900, 2017). "In conclusion, the masseter levels of IL-6, IL-7, IL-8 and IL-13 were elevated in patients with TMD myalgia and increased in response to tooth-clenching." (PMID 28243900, 2017). "This is the first study to show elevated muscle levels of the pro-inflammatory cytokines IL-6 and IL-8 and the anti-inflammatory cytokines IL-7 and IL-13 in painful jaw muscles of patients with TMD myalgia which supports the hypothesis that patients with TMD myalgia have higher levels of cytokines." (PMID 28243900, 2017).
myalgic encephalomyelitis (3 papers, 2017 to 2025). "A recent study reported that IL-7 was related to musculoskeletal pain and impaired cognitive processing in patients with myalgic encephalomyelitis and chronic fatigue syndrome." (PMID 35628904, 2022). "In addition, analyses of serum from myalgic encephalomyelitis and chronic fatigue syndrome patients (conditions that are considered closer to GWI patients) have revealed decreased levels of IL-16 and IL-7." (PMID 28659758, 2017).
myasthenia gravis (3 papers, 2019 to 2025). Myasthenia gravis (MG) is a rare, clinically heterogeneous, autoimmune disorder of the neuromuscular junction characterized by fatigable weakness of voluntary muscles. "Furthermore, decreased expression of miR-181c in peripheral blood mononuclear cells from patients with myasthenia gravis correlates with elevated serum IL-7 and IL-1732." (PMID 31673072, 2019).